RN7SL505P (RNA, 7SL, cytoplasmic 505, pseudogene)
Gene: Miscellaneous RNA gene on chromosome 7 (33,045,798 to 33,046,090, reverse strand). Ensembl gene ENSG00000241420.
Homologues: Orthologues: chimpanzee Metazoa_SRP (98% identical), macaque Metazoa_SRP (93% identical). Paralogues in human: RN7SL2 (82% identical), RN7SL1 (81% identical), RN7SL126P (81% identical), RN7SL3 (80% identical), RN7SL769P (80% identical), RN7SL679P (80% identical), RN7SL220P (79% identical), RN7SL411P (79% identical), RN7SL493P (79% identical), RN7SL650P (79% identical), RN7SL426P (78% identical), RN7SL803P (78% identical), and 699 more.